GPX3 (glutathione peroxidase 3)
Description:
Protects cells and enzymes from oxidative damage, by catalyzing the reduction of hydrogen peroxide, lipid peroxides and organic hydroperoxide, by glutathione.
Synonyms: GSHPx-3; GPx-P; GSHPx-P
Tractability: Small molecule: it has a binding pocket of medium quality. Antibody: its Gene Ontology location is reachable by antibodies, with high confidence; UniProt places it where antibodies can reach, with medium confidence; UniProt predicts a signal peptide or a membrane-spanning region.
Gene: Protein-coding gene on chromosome 5 (151,020,591 to 151,028,988, forward strand). Ensembl gene ENSG00000211445.
Subcellular location: Secreted
Pathways (Reactome):
Cellular responses to stimuli: Detoxification of Reactive Oxygen Species
Gene Ontology:
Molecular function: glutathione peroxidase activity; identical protein binding; protein binding; selenium binding; peroxidase activity
Biological process: cellular response to oxidative stress; hydrogen peroxide catabolic process; response to lipid hydroperoxide; cellular oxidant detoxification; response to oxidative stress
Cellular component: extracellular exosome; extracellular region
Genetic constraint (gnomAD): Loss-of-function variants: 23 observed, 22.62 expected, observed/expected ratio (o/e) 1.02, 90% interval 0.73 to 1.44. The upper end of that interval is the gene's LOEUF score, 1.44, which puts it in group 5 of 6, group 1 being the genes least tolerant of losing a copy. Missense variants: 268 observed, 285.79 expected, observed/expected ratio (o/e) 0.94, 90% interval 0.85 to 1.04. Synonymous variants: 107 observed, 114.47 expected, observed/expected ratio (o/e) 0.93, 90% interval 0.8 to 1.1.
Homologues: Orthologues: chimpanzee GPX3 (99% identical), macaque GPX3 (96% identical), rat Gpx3 (91% identical), mouse Gpx3 (89% identical), guinea pig GPX3 (85% identical), pig GPX3 (77% identical), rabbit GPX3 (65% identical), zebrafish gpx3 (54% identical), tropical clawed frog gpx3 (43% identical), zebrafish gpx1a (36% identical), Caenorhabditis elegans gpx-3 (35% identical), Caenorhabditis elegans gpx-5 (35% identical), and 6 more. Paralogues in human: GPX6 (68% identical), GPX5 (67% identical), GPX1 (38% identical), GPX2 (35% identical), GPX4 (27% identical), GPX7 (23% identical), GPX8 (23% identical).
Diseases named in the same sentence as GPX3 in open-access papers:
GPX3 is named in the same sentence as 232 diseases in open-access papers, as found by Europe PMC text mining. Sharing a sentence is not in itself a finding about the gene and the disease. The quoted sentences say what the papers report.
prostate carcinoma (38 papers, 2009 to 2024). A carcinoma that arises from epithelial cells of the prostate gland. "Loss of Gpx3 induces oxidative stress and increases prostatic intraepithelial neoplasia proliferation in prostatic cancer, and silencing GPX3 expression has been reported to enhance metastasis of human thyroid cancer." (PMID 37107573, 2023). "GPX3, which can be found in the extracellular space and in circulation, is downregulated in several cancers including bladder, breast, cervical, lung, and prostate cancers, The downregulation of GPX3 is negatively associated with increased lipid peroxidation." (PMID 36358931, 2022). "Currently, GPx3 is considered a new tumor-suppressor gene, and its hypermethylation, which is associated with the further down-regulation of GPx3, was observed in patients with Barrett’s esophagus, endometrial adenocarcinoma and prostate cancer." (PMID 32571353, 2020). "Complete inactivation of the GPX3 gene by genetic loss of one allele and methylation-mediated silencing of the remaining allele was also reported in prostate cancer." (PMID 23071548, 2012). "It has been reported that GPX3 deficiency could enhance the cell proliferation of prostate cancer (PCa) tissues and reduce PCa cell apoptosis." (PMID 37633909, 2023). "The changes in activity of GPX1, GPX2, and GPX3 isoforms may be associated with the development of cancers, for example, prostate cancer or even colon cancer." (PMID 26682223, 2015). "Research indicates that the dysfunction of GPX3 expression in tumor cells is linked to a poor prognosis for patients with cancer and chemotherapeutic resistance 44, including endometrial adenocarcinoma 45, lung cancer 46, gastric cancer 47, prostate cancer 48, cervical cancer 49, and thyroid cancer." (PMID 38774759, 2024). "GPX3 was downregulated in breast, colorectal, lung, and prostate cancers, with GPX2 showing a similar pattern in all but colorectal and prostate cancers." (PMID 39594421, 2024). "Additional studies in prostate cancer and thyroid cancer showed that the overexpression of GPX3 reduces metastasis." (PMID 37175499, 2023). "Regarding GPx3, it can be considered a novel tumor-suppressor gene because hypermethylation is detected with down-regulation of GPx3 in tumor patients with Barrett’s esophagus, prostate cancer, and endometrial adenocarcinoma." (PMID 38202704, 2023). "In prostate cancer, GPx3 overexpression induces downregulation of the oncogene c-met, although the mechanisms of this were not explored." (PMID 32781581, 2020). "The downregulation of GPx3 has been observed in numerous cancers including hepatocellular carcinoma, prostate cancer, gastric cancer, Barrett’s adenocarcinoma, glioblastoma, and cervical cancer." (PMID 33255360, 2020). "GPx3 overexpression decreases clonogenic growth, in vivo xenograft tumor size, and metastasis of prostate cancer cells." (PMID 32781581, 2020). "For example, when GPX3-/- mice are crossed with the transgenic adenocarcinoma of the mouse prostate (TRAMP) mice, loss of GPx3 increases the incidence of prostate cancer in this model." (PMID 32781581, 2020). "More recently, the overexpression of GPX3 has been reported in prostate cancer, gastric cancer, CRC pathogenesis and leukaemia stem cells." (PMID 31467500, 2019). "And other recent studies showed the involvement of GPx3 in the pathogenesis of other human cancers such as gastric, ovarian and prostate cancer." (PMID 28837649, 2017). "Overexpression of GPX3 in prostate cancer cell lines seemed to restrain tumor growth and metastasis through downregulation of c-met, a receptor tyrosine tumor transforming gene involved in a variety of cellular processes." (PMID 25970749, 2015). "Downregulation of GPX3 expression by promoter hypermethylation has been reported in 71.4% of esophageal squamous cell carcinoma, 83% of gastric cancer and 90% of prostate cancer, indicating its possible suppression by epigenetic change in ccRCC." (PMID 25970749, 2015).
prostate carcinoma (continued). "Reduced GPX3 expression has been found in prostate cancer, in endometrial cancer, and in head and neck cancer as well." (PMID 26682223, 2015). "GPX3 promoter hypermethylation and downregulation were detected in prostate cancer; endometrial adenocarcinoma; cervical, thyroid, and lung cancer; head and neck carcinoma; gastric cancer; and multiple myeloma." (PMID 24790704, 2014). "GPx3 has been reported to commit its tumor suppressive activity through inhibition of c-Met expression in prostate cancer." (PMID 25333265, 2014). "On the contrary, GPX3 was found to be downregulated in carcinoma tissues of breast, gastric, and colorectal cancer patients, prostate cancer, thyroid cancer, and esophageal cancer." (PMID 24790704, 2014). "GPX3 has been found to be frequently hypermethylated in prostate cancer, esophageal adenocarcinoma, and gastric cancer." (PMID 25050929, 2014). "Aneuploidy, loss of heterozygosity, gene mutations, hypermethylation and inactivation of specific tumour suppressor genes such as GSTpi, APC, MDR1, GPX3 and others have been detected in prostate cancers, but generally only at a low or moderate frequency." (PMID 24282788, 2013). "Over expression of GPX3 led to significant reduction of invasiveness in human prostate cancer cells, PC3, DU145, and LNCaP in vitro." (PMID 23567478, 2013). "GPX3 is often down-regulated in prostate cancer cells and is considered to be a tumor suppressor gene." (PMID 23567478, 2013). "GPX3 has also been suggested as a novel tumor suppressor gene due to its ability to reduce prostate cancer cell invasiveness, tumor volume and metastasis." (PMID 24358304, 2013). "Downregulation of GPX3 has been reported in human cancers such as lung, ovarian, bladder, esophageal, and prostate cancer, as well as in gastric cancers." (PMID 23071548, 2012). "The GPX3 gene was shown to display epigenetic inactivation in prostate cancer, ovarian clear cell adenocarcinoma, gastric carcinoma and Barret's disease." (PMID 21106063, 2010). "The gene expression of GPX3 in human has previously been shown to be silenced in prostate cancer, ovarian clear cell adenocarcinoma, gastric carcinoma and in Barret's disease by epigenetic mechanisms, such as hyper-methylation." (PMID 21106063, 2010). "In previous studies in human prostate cancer, it was suggested that GPX3 exhibits tumor suppressor activity by transcriptional regulation of the oncogene MET." (PMID 21106063, 2010). "Gpx3 has been found to be either deleted or highly methylated in exon 1 in prostate cancer cell lines and in Barrett's tumorigenesis and has been suggested to exhibit tumor suppressor activity." (PMID 19426485, 2009). "GPx3 has been reported as an important regulator for numerous cancers, e.g., lung cancer, esophageal carcinoma, melanoma, prostate cancer, hepatocellular carcinoma, bladder cancer, and ovarian cancer." (PMID 37484915, 2023). "As a result, GPX3 assumes a significant function in the regulation of cellular proliferation and differentiation, as well as the invasiveness and motility of various cancers such as prostate cancer 25, melanoma 26, GC 29, and other cancers." (PMID 37790850, 2023). "Specifically, the over-expression of GPX3 could decrease the clonogenic growth, xenograft tumor size, and migration and invasion of prostate cancer cells." (PMID 35978348, 2022). "Reduced GPx3 expression inhibited the survival of clonal and unanchored cells and prostate cancer." (PMID 34926458, 2021). "In addition to gene methylation, GPX3 gene deletions have been reported in prostate cancer, occurring in 39% of samples studied." (PMID 32781581, 2020). "An alternate tumor suppressive function for GPx3 was discovered in prostate cancer cell lines." (PMID 32781581, 2020).
prostate carcinoma (continued). "GPx3 is considered to be a novel tumor suppressor, since hypermethylation of the GPx3 was detected in tumor samples from patients with Barrett’s esophagus, endometrial and prostate cancer, and down-regulation was generally correlated with worse prognosis." (PMID 29108391, 2017). "Moreover, GPX3 downregulation was reported in prostate cancer tissues, thyroid cancer, and esophageal cancer." (PMID 24790704, 2014). "A recent study has demonstrated that GPX3 can suppress prostate cancer growth and metastasis." (PMID 23071548, 2012). "Because GPX3 has been suggested to be a potential tumor suppressor in prostate cancer, we hypothesized that GPX3 may have the similar tumor suppressor function in gastric cancer." (PMID 23071548, 2012). "Moreover, xenografted prostate cancer cells expressing GPX3, showed reduction of tumor size, elimination of metastasis and reduction of animal death." (PMID 21106063, 2010). "GPX3 may be a tumor and metastasis suppressor in prostate cancer." (PMID 23567478, 2013). "GPX3 gene codes for the Glutathione peroxidase 3, also known as plasma glutathione peroxidase (GPx-P), the variations in activity of GPX1, GPX2, and GPX3 isoforms may be associated with the development of cancers, for example, prostate cancer or even colon cancer." (PMID 27874091, 2016).
gastric cancer (37 papers, 2010 to 2026). A primary or metastatic malignant neoplasm involving the stomach. "GPx3 has been found to inhibit the proliferation and metastasis of lung and liver cancer cells, while reduced GPx3 activity is linked to cancers of the stomach, prostate, skin, and others." (PMID 40332015, 2025). "In the Taiwanese population, the expression of GPX3 rs3805435 and rs3828599 showed a significant association with the risk of developing gastric cancer." (PMID 39125992, 2024). "Patients with gastric cancer who have a promoter or copy number decrease inactivating the GPX3 gene are at greater risk of lymph node metastases." (PMID 35069731, 2022). "Silencing of GPx3 through DNA hypermethylation is associated with lymph node metastasis in gastric cancer and cervical cancer." (PMID 34926458, 2021). "Recently, we found that inactivation of the GPX3 gene by promoter hypermethylation in gastric cancer is associated with high incidence of lymph node metastasis." (PMID 24790704, 2014). "In conclusion, our results suggest that GPX3 gene inactivation by promoter methylation and/or copy number loss is a frequent finding in gastric cancer that correlates with increased incidence of lymph node metastasis." (PMID 23071548, 2012). "The downregulation of GPX3 expression and GPX3 promoter hypermethylation were significantly associated with gastric cancer lymph node metastasis (P = 0.018 and P = 0.029, respectively)." (PMID 23071548, 2012). "This indicates that the systems that regulate ROS have been disrupted, and GPX3 may be implicated in the development of gastric cancer, as shown by our results when evaluated alone and in combination." (PMID 35069731, 2022). "GPX3 rs3805435 heterozygote G allele, rs3828599 heterozygote T allele, and rs2070593 heterozygote A allele are shown to be associated with decreased risk for gastric cancer as well." (PMID 32781581, 2020). "Furthermore, we found that promoter methylation and loss in copy number of GPX3 gene are associated with the number of lymph node metastases in gastric cancer." (PMID 24790704, 2014). "In addition, we found that loss in DNA copy number, hypermethylation of the promoter region, and downregulation of mRNA expression of GPX3 are associated with lymph node metastasis in gastric carcinomas." (PMID 24790704, 2014). "We also detected a significant loss of DNA copy number of GPX3 in gastric cancers (P<0.001)." (PMID 23071548, 2012). "In addition to Se deficiency, association studies of single nucleotide polymorphisms (SNP) in the GPX3 gene suggest that certain GPX3 SNPs may be associated with colorectal and gastric cancers." (PMID 32781581, 2020). "GPX3 rs736775 C allele indicated better survival in colorectal cancer, and in gastric cancer, GPX3 rs736775 TC/CC may be considered a prognostic marker since it was associated with improved overall survival in patients that received platin and fluorouracil-based adjuvant chemotherapy." (PMID 32781581, 2020). "Therefore, our results showing frequent loss of GPX3 expression in gastric cancer may underscore the failure in the cellular antioxidant system which is the first line of defense against detrimental ROS activity." (PMID 23071548, 2012). "In the current study, we have demonstrated promoter hypermethylation and DNA copy number loss as possible mechanisms mediating silencing of GPX3 in gastric cancers, although other mechanisms such as gene mutation and miRNA regulation may also be involved and need to be further studied." (PMID 23071548, 2012). "These key genes (UGT1A1, ADH4, ADH1B, CYP19A1, and GPX3) are crucial for the construction of our gastric cancer (GC) prognostic model." (PMID 41031088, 2025). "The expression of GPX3 rs736775 in patients with gastric cancer undergoing adjuvant chemotherapy with platinum and fluorouracil has been associated with enhanced overall survival." (PMID 39125992, 2024).